MCM10 (minichromosome maintenance 10 replication initiation factor)
Diseases named in the same sentence as MCM10 in open-access papers (continued):
Sharing a sentence is not in itself a finding about the gene and the disease.
tumor (41 papers, 2013 to 2025). "Our findings suggest that in the great majority of tumor types, increased MCM10 expression is linked to a poor prognosis." (PMID 37848534, 2023). "As a potential target for tumor treatment and a promising prognostic and diagnostic biomarker for immunomodulation, MCM10 exhibits promise." (PMID 37848534, 2023). "MCM2, MCM3, MCM6, MCM8, MCM9, and MCM10 groups significantly varied and associated with the tumor stages." (PMID 34490114, 2021). "In our analysis of GSE1561, MCM10 was one of the hub genes in the blue module which was significantly associated with tumor grade." (PMID 30254986, 2018). "We observed a significant association between high MCM10 mRNA expression with tumor grading and patients’ survival time." (PMID 30135378, 2018). "In the initial study, both MCM2 and MCM10 overexpression were significantly associated with primary tumor status in UTUC (P=0.048 and 0.004, respectively) and UBUC (P=0.005 and 0.004, respectively)." (PMID 27780919, 2016). "We demonstrated that MCM10 immunoexpression was significantly associated with aggressive pathological features, including advanced primary tumor status, vascular invasion, and nodal metastasis in both groups of UCs." (PMID 27780919, 2016). "MCM10 has been highlighted for its significant overexpression in various cancer tissues and its association with tumor aggressiveness, immune cell infiltration, immune checkpoints, tumor mutational burden (TMB), and microsatellite instability (MSI)." (PMID 40255404, 2025). "The findings demonstrated that tumor type affected the frequency of MCM10 mutations." (PMID 37848534, 2023). "MCM10 may be a good target for tumor immunotherapy and may be significant in tumor immunotherapy, according to the significant association between MCM10 and immunological checkpoints." (PMID 37848534, 2023). "Moreover, histologic grade, clinical stage, tumour invasion, primary therapy outcome and lymphatic metastasis were identified to be associated with MCM10 protein expression." (PMID 37246638, 2023). "Through bioinformatic analysis based on TCGA database, we found that age, tumour invasion, histological type, histologic grade, clinical stage and primary therapy outcome were identified to be associated with the expression of MCM10 mRNA." (PMID 37246638, 2023). "Together, this research demonstrates MCM10 may be both a mediator pathogenic tumor growth and a valuable diagnostic marker." (PMID 33604163, 2021). "MCM2-7 and MCM10 expressions were associated with WHO tumor grade." (PMID 25046975, 2014). "The findings indicate that MCM10 serves as a poor prognostic marker in EC, as its overexpression is associated with tumour progression, aggressive clinicopathological features, and reduced overall survival, suggesting that MCM10 may promote EC development and could be a potential therapeutic target." (PMID 41312167, 2025). "For example, IHC confirmation helped to validate the computationally predicted MCM10 in EC progression—demonstrating high concordance between the elevated protein expression and tumour invasiveness." (PMID 41312167, 2025). "These genes formed a highly interconnected network, with key central nodes such as AURKB, CEP55, CCNB2, and MCM10, suggesting their involvement in common pathways potentially driving aggressive tumor behavior and contributing to poor patient prognosis." (PMID 39596419, 2024). "Possible relationships between MCM10 and clinical staging, diagnosis, prognosis, Mutation burden (TMB), microsatellite instability (MSI), immunological checkpoints, DNA methylation, and tumor stemness were identified." (PMID 37848534, 2023). "More specifically, the mRNA expressions of MCM10 were higher in the groups of age > 60, tumour invasion > = 50%, serous type, grade 2 (G2), grade 3 (G3), stage III and IV and part response (PR) compared with that in the control groups (p < 0.05)." (PMID 37246638, 2023).
tumor (continued). "The ongoing subject is to dissect further the influence of differential expression of MCM10 on tumor growth and its resistance to PTX in mice by constructing a GC mouse xenograft model." (PMID 37860833, 2023). "But the results form immunohistochemistry suggested that the expression of MCM10 protein was closely related to clinical stage and tumour invasion of UCEC patients." (PMID 37246638, 2023). "The findings demonstrated that MCM10 expression was elevated in the majority of cancer types and was connected to tumor dryness, immunocytic infiltration, immunological checkpoints, TMB and MSI." (PMID 37848534, 2023). "The connection between MCM10 expression and ICPs expression in pan-cancer was investigated to ascertain the potential of MCM10 as a target for tumor immunotherapy." (PMID 37848534, 2023). "More specifically, the protein expressions of MCM10 were higher in the groups of G2 and G3, tumour invasion > = 50%, stage III and IV, lymphatic metastasis and PR compared with in the control groups (p < 0.05)." (PMID 37246638, 2023). "The mRNA expression levels of the MCMs were significantly increased in tumour tissues compared to normal, and MCM10 showed a fold change of 3.4." (PMID 39086679, 2023). "Among all the MCMs, the RNA levels of MCM10 in the tumor showed a 3.4-fold increase compared to the control." (PMID 39086679, 2023). "Despite these results, more investigation is required to elucidate the additional functions that MCM10 plays in tumor growth and progression." (PMID 37848534, 2023). "The relationship between MCM10 expression and immune infiltration in OV was investigated using the Tumor Immunology Estimation Resource database." (PMID 35664337, 2022). "MCM10 expression was found consistently and significantly higher in tumors with a higher malignancy, a higher tumor grade, and highly aggressive cancer cell lines." (PMID 35813483, 2022). "IHC staining of MCM10 showed relatively higher and distinct expression of MCM10 in different grades of tumors, i.e. higher the tumor grade, higher the MCM10 expression." (PMID 35813483, 2022). "There is accumulating evidence suggesting that in the development of tumor, dysregulation of MCM10 contributed to aberrant proliferation and genome instability." (PMID 34239894, 2021). "In consistent with these finding, here our study also found that MCM10 is overexpressed in tumor tissues of ESCC and prominently correlated with the inferior survival of ESCC patients." (PMID 34185429, 2021). "Our findings suggest that MCM family members play crucial roles in BC progression, and MCM2, MCM4–7, and MCM10 in tumor tissues possess great potential to be valuable prognostic biomarkers for BC patients." (PMID 34475953, 2021). "It is emerging as a promising anti-cancer target as MCM10 expression correlates with tumour progression and poor clinical outcomes." (PMID 31409229, 2019). "To further understand the effect of MCM10 knockdown on tumor growth in vivo, we grafted MCF 7 knockdown cells into the mammary fat pad of nude mice." (PMID 30135378, 2018). "The tumors formed by MCM10 knockdown cells showed a significant decrease in MCM10 expression compared to the control cells, suggesting that reduction of MCM10 also reduced tumor growth in vivo in mice models." (PMID 30135378, 2018). "MCM10 mRNA expression was found to be significantly higher (p = 0.006) in tumor samples compared to the respective normal tissue." (PMID 30135378, 2018). "Correspondingly, evaluation of MCM10 mRNA expression in 36 UTUCs and 30 UBUCs showed significantly upregulated levels in high stage UC, suggesting its role in tumor progression." (PMID 27780919, 2016). "The observed upregulation of MCM10 mRNA in ccRCC tumors from M1 patients as shown in our study is in line with a higher proliferative activity of the transformed primary tumor." (PMID 26859141, 2016).
tumor (continued). "Frequent over expression of MCM10, which partners with RECQL4 and binds to MCM2-7 complex activating its helicase activity, indicates that MCM10 is critical in the tumor progression." (PMID 23874974, 2013). "Maximum change was observed in the expression levels of MCM10 i.e. an average of 22.9 (±17.33) fold change in tumor and 20.14 (±12.7) fold change in cell lines." (PMID 23874974, 2013). "Expression level of MCM10 in tumor (0.367±0.277, median = 0.315) and cell lines (0.325±0.205, median = 0.35) is significantly different (p = 0.0001) from that of normal (0.016±0.022, median = 0)." (PMID 23874974, 2013). "MCM10 knockdown inhibits tumor sphere formation and PTX resistance." (PMID 40977684, 2025). "Additionally, we analyzed several markers known to indicate the progression of tumor cell growth such as Aurka (Aurora kinase A), Ki67 and MCM10, to estimate the level of tumor cell repopulations incubated in CMs with distinct contents of Hsp70." (PMID 37880798, 2023). "Moreover, the expression levels of BUB1, BUB1B, CDK1, CCNA2, MCM10 were significantly higher in CRC tumor tissues compared with normal tissues based on the GEPIA database." (PMID 37466419, 2023). "The function of MCM10 might be mainly involved in DNA replication, cell cycle, DNA repair and tumour immune microenvironment." (PMID 37246638, 2023). "Finally, we confirmed the function of MCM10 as a possible target for tumor therapy by examining the link between MCM10 expression and drug sensitivity." (PMID 37848534, 2023). "Furthermore, the logistics regression analysis showed that tumour invasion > = 50% and stage III and IV were risk factors of MCM10 protein high expression in UCEC." (PMID 37246638, 2023). "We also evaluated MCM10 expression in relation to pan-cancer tumor stage." (PMID 37848534, 2023). "In summary, MCM10 has a variety of impacts on immunity to various tumor types in the tumor microenvironment and may play a role in mediating the tumor immune response." (PMID 37848534, 2023). "We discovered that MCM10 had substantial relationships with several immune checkpoints, which suggests that MCM10 could act as a novel immune checkpoint for tumor immunity." (PMID 37848534, 2023). "Knockdown of MCM10 notably repressed the formation of AGS/PTX-based tumor spheroids." (PMID 37860833, 2023). "Of these, miR-485-3p, a tumor suppressor in GBM was presumed to inhibit MCM10 and MELK." (PMID 35109908, 2022). "Interestingly, MCM10 expression was found consistently and significantly higher in tumors with a higher malignancy and a higher tumor grade." (PMID 35813483, 2022). "Moreover, MCM10 expression was presented extensively to be upregulated level in tumor tissues of other cancer types, and the amplification of MCM10 also frequently occurred across multiple cancer types, including ESCC, from the TCGA database." (PMID 34185429, 2021). "Therefore, it is not surprising that MCM10 is commonly upregulated in cancer cell lines and tumor samples, suggesting that transformed cells rely on MCM10 to prevent genome instability from reaching lethal levels." (PMID 33712616, 2021). "Finally, we validate these results in clinical biopsy specimens and show that tumor size is proportional to MCM10 expression levels." (PMID 33604163, 2021). "Considering that aberrant overexpression of MCM10 in ESCC tumor cells might induce DNA over‐replication, moderately decreasing expression of MCM10 might be helpful for suppressing the proliferation and migration of ESCC cells." (PMID 34185429, 2021). "Decreased survival was observed in Kaplan Meier survival curves for cases with MCM 2, 4, and 5, CDC45, GINS1, and MCM10 expression above the tumor cohort average, in agreement with the general concept that high expression of proliferation genes correlates with decreased survival." (PMID 31857847, 2019).
tumor (continued). "Furthermore, the level of MCM10 upregulation in some cancers has been correlated with tumour progression or poor clinical outcomes." (PMID 31409229, 2019). "We isolated the tumor on the 14th week and analyzed expression of MCM10 using qPCR." (PMID 30135378, 2018). "Finally, MCM10 expression is often increased in rapidly proliferating tumor cells (discussed in more detail below), pointing to a potential role in not just facilitating but actively driving cell cycle progression." (PMID 28218679, 2017). "Notably, a higher number of MCM10 alterations have been identified in breast cancer samples than in other tumor types." (PMID 28218679, 2017). "Interestingly, MCM10 overexpression increases with advancing tumor stage in cervical cancer and correlates with the transition from confined to metastasized renal clear cell carcinoma." (PMID 28218679, 2017). "We found a significant increase in MCM2 (3.5 fold), MCM3 (3.1 fold), MCM4 (4.3 fold), MCM5 (3.8 fold), MCM6 (3.5 fold), MCM7 (3.0 fold) and MCM10 (3.6 fold) expressions in tumor tissues (the average fold value of three grades) compared to the normal brain controls." (PMID 25046975, 2014). "Mean expression level of MCM10 increases according to the increasing tumor stages." (PMID 23874974, 2013). "In our study, the expression level of MCM10 was found to be related to multiple clinical features that were associated with the development of UCEC, including age, histological type, histologic grade, tumour invasion, clinical stage, primary therapy outcome and lymphatic metastasis." (PMID 37246638, 2023). "Moreover, our ongoing studies also suggest that MCM10 may act as an oncogene that is critical for the malignant proliferation of tumor cells." (PMID 37848534, 2023). "Tumor tissues exhibited elevated expression levels of CYP26B1, MCM10, SPINK4, and TRIM54 compared to normal liver tissues, as indicated by the results." (PMID 38870259, 2024). "Immunohistochemistry analysis showed that CYP26B1, MCM10, SPINK4, and TRIM54 were highly expressed in tumor tissue compared to normal tissue." (PMID 38870259, 2024). "Tumor tissues exhibited high expression levels of CYP26B1, MCM10, SPINK4, and TRIM54 in the current study." (PMID 38870259, 2024). "Comparing polymerase components across thirty-seven tumor types revealed a common subset with elevated transcriptional pattern typified by POLE2 and POLQ that included EXO1, MCM10, GINS2, CDT1, ORC6L, and BLM." (PMID 31857847, 2019). "A comparison of the distribution of MCM genes between tumor and adjacent normal lung tissues showed MCM2-8 and MCM10 to be significantly up-regulated in LUAD tumor tissues in TCGA cohorts, whereas the SRF and MCM9 were significantly down-regulated in the same." (PMID 31323040, 2019). "Other examples include MCM10 and CCND1 also targeted by miR-199a-5p, PBK, that promotes tumour cell proliferation through p38 MAPK activity that is targeted by miR-28-5p and cyclin genes CCND1 and CCND2 targeted by miR-150." (PMID 25200074, 2014). "MCM5 (40%), MCM6 (45.5%) and MCM9 (25%) were moderately higher in tumor tissues than in normal tissues, and MCM10 was negative in most (91.7%) tumor tissues." (PMID 34859821, 2021). "Many studies have described MCM10 overexpression in a variety of cancer types, wherein the extent of upregulation corresponded with tumor progression and negative clinical outcomes." (PMID 33712616, 2021). "As expected, in our report, the expression of MCM8 and MCM9 was not significantly higher in EC and was even lower in the tumor tissue, but MCM10 was highly expressed in tumors." (PMID 34859821, 2021). "Many of the key regulators in the canonical oncogenic (tan) module were involved in the processes leading to tumor cell proliferation and survival (TPX2, NCAPH, KIF11, NUSAP1, KIF23, MCM10) but most of them have not been associated with pediatric tumors." (PMID 31988326, 2020).
tumor (continued). "ROC curve indicated that CCNB2, FBXO5, KIF4A, MCM10, and TPX2 exhibited excellent diagnostic efficiency for normal and tumor tissues." (PMID 30254986, 2018). "This is consistent with the previous study that the suppression of cell cycle regulators was accompanied by the down-regulation of a number of genes directly involved in the process of DNA replication (MCM10, ORC1) when tumor cells were subjected to fullerene for 48 h64." (PMID 29795396, 2018). "Minichromosome Maintenance Complex Component 10 (MCM10), overexpressed 4.2-fold in resistant tumors, activates Aldehyde Dehydrogenase 1 Family Member A1(ALDH1A1) and SRY-Box Transcription Factor 2 (SOX2) to promote stemness, evidenced by tumor sphere enlargement." (PMID 40977684, 2025). "Finally, the five candidate genes DNMT3B, EXO1, MCM10, CENPF and CENPE were combined in a new prognosis tool, Gene Expression Classifier or GEC, that stratifies patients according to the number of activated genes in the corresponding tumour (activation status ON)." (PMID 37592220, 2023). "Not all but some of the genes as MCM4, MCM6, MCM10 and RECQL4 show a positive trend with increasing tumor stages." (PMID 23874974, 2013).